STAT3 (signal transducer and activator of transcription 3)
Diseases named in the same sentence as STAT3 in open-access papers (continued):
Sharing a sentence is not in itself a finding about the gene and the disease.
tumor (continued). "STAT3 inhibition in many tumor models/primary tumor cells leads to loss of survival and proliferation, suggesting addiction of tumor cells to STAT3 activity." (PMID 25089666, 2014). "On a similar note, hyperactivation of STAT3 in CT26 or C6 tumor cells was implicated for the abnormal differentiation of DCs in cultures containing conditioned media." (PMID 24806510, 2014). "In search for a possible mechanism for the activation of the STAT3 signaling pathway, we observed that silencing interleukin (IL)-6 in tumor-associated endothelial cells inhibited STAT3 phosphorylation in tumor cells." (PMID 24533454, 2014). "Then, STAT3 phosphorylation at Y705 triggers its dimerization, resulting in the translocation of cytoplasmic STAT3 into the nucleus and transcription of targeting genes associated with tumor metastasis." (PMID 24846175, 2014). "STAT3 deletion in hematopoietic cells has been associated with a markedly decreased number of tumor-infiltrating Treg cells, as well as enhanced activity of DCs, natural killer (NK) cells, T cells, and neutrophils." (PMID 24518612, 2014). "Constitutive activation of signal transducer and activator of transcription-3 (STAT3) has been implicated as a central mechanism of tumor-induced immunosuppression." (PMID 24806510, 2014). "The results also revealed that PKR activates STAT3, a transcription factor associated with primary liver tumors, which is suggested to promote tumor cell proliferation." (PMID 25360179, 2014). "The STAT3 pathway is more highly activated in response to several cytokines, including IL-1β, IL-4 and IL-10 in tumor-associated macrophages of the M2 phenotype than in M1 macrophages." (PMID 25198511, 2014). "In this study, tumor size larger than 2 cm was the only clinicopathologic parameter associated with lower STAT3 activity." (PMID 24662939, 2014). "NK cell cytotoxicity is significantly lower against STAT3-deficient compared to STAT3-expressing tumor cells." (PMID 24473086, 2014). "Tumor-associated Tregs express the IL-23 receptor, which activates Stat3, resulting in the upregulation of the Treg-specific transcription factor Foxp3 and the immunosuppressive cytokine IL-10." (PMID 24586528, 2014). "Potential drugs that directly inhibit STAT3 activation include the naturally occurring triterpenoid oleanolic acid, which also suppresses the M2 polarization of tumor-associated macrophages by suppressing IL-10 secretion." (PMID 24518612, 2014). "Previous studies have reported that STAT3 levels in B cells are associated with tumor growth, therefore, the present study investigated the effect of JSI124-treated 4T1 mouse-derived B cells on 4T1 tumor growth in vivo." (PMID 25013518, 2014). "This suggests that STAT3 is a positive regulator of β-catenin and is supported by our analysis of primary tumours showing a positive association between nuclear β-catenin and nuclear STAT3 expression." (PMID 25348333, 2014). "In the initiation stage of CAC, IL-6 acts as a tumor promoter by binding to its gp130-associated receptor and activated Stat3 signal pathway, which is the major protumorigenic effector for IL-6." (PMID 25093140, 2014). "Our study supports the widely held tenet that inhibition of STAT-3 activation is an attractive strategy for modulating the expression of genes implicated in tumour development and progression." (PMID 25296162, 2014). "It is well known that signal transducer and activator of transcription 3 (STAT3) is involved in the creation of the tumor microenvironment and tumor development due to its association with immunosuppression, angiogenesis, and cancer cell proliferation." (PMID 24738052, 2014). "Accumulating evidence has identified STAT3 as a critical molecule in regulating tumor-associated immunosuppression by interfering with multiple factors." (PMID 25594054, 2014).
tumor (continued). "Because STAT3 induces the expression of cytokines, growth factors and angiogenic factors, and the associated receptors in turn activate STAT3, a feedforward loop is established between tumor cells and immune cells." (PMID 25149535, 2014). "In tumor cells, constitutive activation of STAT3 can be caused by abnormal and sustained autocrine and/or paracrine signaling including interleukin-6 (IL-6) signaling." (PMID 23658720, 2013). "The availability of both loss-of-function and gain-of-function mouse models for Stat3 in skin keratinocytes facilitated further study of this important molecule in skin carcinogenesis mediated by ultraviolet B (UVB) exposure." (PMID 23577258, 2013). "In the tumor microenvironment, STAT3 mediates multidirectional crosstalk between tumor-associated myeloid cells and other stromal cells, including endothelial cells." (PMID 23717691, 2013). "Recently, STAT3 activation has been associated with tumor initiating cell phenotype of liver, colon and glial cancer cells." (PMID 24344100, 2013). "In GBM, the transcription factors NF-κB and STAT3 are aberrantly activated and associated with tumor cell proliferation, survival, invasion and chemoresistance." (PMID 24244348, 2013). "Jak2/STAT3 signaling has been also shown to play a crucial role in tumor-associated MDSC generation." (PMID 24066282, 2013). "STAT3 is a critical link between tumor cells and their microenvironments by regulating both tumor growth and tumor-associated inflammation." (PMID 23940556, 2013). "Here, we show that tumor-associated B cells with activated STAT3 contribute to tumor development by promoting tumor angiogenesis." (PMID 23734190, 2013). "Tumor-associated fibroblasts were found to secret IL-6 and the conditioned medium harvested from the fibroblasts also induced STAT3 activation in NPC cells." (PMID 24380387, 2013). "In vivo orthotopic animal model results show that knockdown of STAT3 caused a significant reduction in tumor burden and delayed tumor progression with increased response to gemcitabine associated with a decrease in the Ki-67 positive cells." (PMID 24025152, 2013). "This study employed HC as an inhibitor of STAT3 activation, and demonstrated that HC encapsuled NPs efficiently “re-educated” tumor associated macrophages in vitro to transform from M2 to M1." (PMID 23825527, 2013). "It is observed that aberrant STAT3 activation in tumor cells is associated with cell proliferation, cell survival, invasion, angiogenesis, and metastasis." (PMID 24199193, 2013). "Using a xenograft tumor model, our data demonstrated that IL-6 level positively linked with angiogenesis and STAT3 activation." (PMID 23637926, 2013). "Supporting this, STAT3 is important for regulating multi-directional feed-forward loop between tumor cells, tumor-associated myeloid cells and endothelial cells for tumor angiogenesis." (PMID 23734190, 2013). "Our observation that berberine effectively inhibited activation of STAT3 induced by tumor-associated fibroblasts suggests a role of berberine in modulating the effects of tumor stroma on the growth of NPC cells." (PMID 24380387, 2013). "Constitutive STAT3 signaling not only promotes tumor growth and metastasis, but is also associated with chemotherapeutic resistance of cancer cells." (PMID 24015205, 2013). "The current dogma for the contribution of STAT3 to cancer biology is as a potent transcription factor driving expression of genes controlling numerous hallmark features of tumor cells." (PMID 24312439, 2013). "The constitutive activation of STAT-3 signaling pathway was associated with M2 phenotype and it has been observed in both cancer and tumor-infiltrating inflammatory cells, including TAMs." (PMID 23533994, 2013). "Stat3 activation in tumor cells and tumor-associated inflammatory cells plays a critical role in tumor progression by augmenting tumor survival and tumor angiogenesis and suppressing antitumor immunity." (PMID 24453427, 2013).
tumor (continued). "On the other hand, maintaining NFκB activity in both cancer cells and tumor-associated hematopoietic cells requires Stat3, as it prolongs NFκB nuclear retention." (PMID 24170218, 2013). "For instance, constitutive activation of STAT3 has been related to breast cancer susceptibility cancer 1 (BRCA1) expression in certain tumor cell lines." (PMID 23738079, 2013). "During the course of tumorigenesis, the activity of STAT3 is also elevated in tumor-associated lymphocytes." (PMID 22911830, 2012). "Consistent with this, IL-17A-deficient C57/Bl6 mice are characterized by a reduced Stat3 activation, as well as increased numbers of tumor infiltrating CD4+ and CD8+ T cells, which produce higher amounts of IFN-γ as compared to wild-type littermates." (PMID 22855687, 2012). "Aberrant activation of STAT3 is commonly observed in tumors and is strongly associated with tumor development and progression." (PMID 23118721, 2012). "The antitumor activity of SOID-8 is associated with inhibition of JAK2/STAT3 signaling in these tumor cells." (PMID 23166634, 2012). "Recently, adhesion of MM cells was linked to enhanced STAT-3 mediated IL-6 signaling, supporting further the survival and proliferation of the tumor." (PMID 22558078, 2012). "STAT-3 has recently been implicated in MFG-E8 stimulation of cancer stem cells produced by tumor-associated macrophages." (PMID 22558449, 2012). "The antitumor activity of LLL12 was associated with decreased microvessel density, decreased tumor-associated angiogenic factors, and complete abrogation of phosphorylated STAT3 protein." (PMID 22530037, 2012). "As to this case, inhibition of STAT3 caused decreased production of IL-6.The activation of STAT3 pathway has been studied in patients’ tumor tissue samples." (PMID 22662257, 2012). "STAT3 activation is linked to tumor progression, mainly through promotion of angiogenesis, anti-apoptotic effects and immune escape, and poor prognosis." (PMID 23170117, 2012). "To explore the possible mechanisms underlying the anti-tumor effects of the STAT3 inhibitor in this HCC model, we performed TUNEL and Ki67 staining in liver tumor tissue after DEN exposure in both groups." (PMID 22136659, 2011). "STAT3 has been implicated as being a central regulator of tumor progression through its transcriptional upregulation of VEGF, Mcl-1, and survivin, among others." (PMID 21481226, 2011). "Constitutively activated STAT3 correlates with a more malignant tumor phenotype, resistance to chemotherapy and is also associated with decreased survival in some cancers." (PMID 21575192, 2011). "HCC development is dependent on enhanced production of the tumor promoting cytokines such as IL-6 which causes hepatic inflammation and activation of the oncogenic transcription factor STAT3." (PMID 22032643, 2011). "Such activation of STAT3 in tumor cells and tumor-associated inflammatory cells plays a critical role in tumor progression by augmenting tumor survival and tumor angiogenesis, and suppressing antitumor immunity." (PMID 21943203, 2011). "Persistent activation of STAT3 has been linked with tumour-associated inflammation and suppression of anti-tumour immunity." (PMID 21291541, 2011). "Supporting these findings, in human HCC tissues, IL-17 expression was significantly and positively associated with STAT3 phosphorylation, neutrophil infiltration, and increased tumor vascularity." (PMID 22171994, 2011). "Significant association was observed between STAT3 expression and tumor circumscription (P = 0.001)." (PMID 21575192, 2011). "Supporting these findings, in human HCC tissues, immunostaining indicated that IL-17 expression was significantly and positively associated with STAT3 phosphorylation, neutrophil infiltration and increased tumor vascularity." (PMID 22171994, 2011).
tumor (continued). "The concurrent reduction in STAT3 transcriptional activity of targets such as survivin through decreased DNA binding and loss of STAT3 phosphorylation likely both played a role in the reduced survival of OSA tumor cells observed following exposure to FLLL32." (PMID 21443800, 2011). "The other histopathological factors associated with STAT3 and pSTAT3 expressions were tumor location (P = 0.025, P = 0.027), plane of the tumor (P = 0.011, P = 0.006) and tumor necrosis (P = 0.001, P = 0.002)." (PMID 21575192, 2011). "Future studies will determine why STAT3 inhibitors decrease tumor-associated inflammation while enhancing necrotic-associated inflammation." (PMID 22136659, 2011). "And finally, STAT3 inhibitor treatment in DEN-induced HCC animal not only reduced tumor growth but also ameliorated cancer associated inflammation via inhibiting inflammatory cell STAT3 activation." (PMID 22136659, 2011). "Expression of STAT3 and pSTAT3 was significantly associated with tumor grade (P < 0.001; P < 0.001), tumor location (P = 0.025; P = 0.027), plane of tumor (P = 0.011; P = 0.006), and tumor necrosis (P = 0.001; P = 0.002)." (PMID 21575192, 2011). "The transcription factor STAT3 has been implicated as a key player in several features of malignant neoplasia including tumor cell survival, metastasis, and resistance to chemotherapy." (PMID 21443800, 2011). "Given the role of survivin, VEGF, and MMP2 in tumor cell survival, angiogenesis, and metastasis, we determined if downregulation of STAT3 DNA binding correlated with loss of expression of these STAT3 transcriptional targets in OSA cell lines." (PMID 21443800, 2011). "Activated STAT3 has been shown to protect tumour cells from apoptosis by regulating genes encoding antiapoptosis-associated proteins, such as Bcl-2, Bcl-xl, and Mcl-1." (PMID 20461084, 2010). "IL-6 induction and expression in tumor cells and tumor associated myeloid cells has an important role in chronic inflammatory oncogenic signaling, likely by activation of the STAT-3 transcriptional activator." (PMID 21429243, 2010). "An increasing number of studies have implicated Stat protein activation, particularly Stat3, in transformation and tumor progression." (PMID 20482858, 2010). "Although polarization of naïve CD4 to Th17 as well as Treg cells requires tumour-associated TGFβ in mice, only Th17 differentiation requires Stat3 activity." (PMID 20478049, 2010). "The presence of phosphorylated STAT-3 (p-STAT-3) in the tumor can induce p-STAT-3 in tumor-associated immune cells that can return to the circulatory system." (PMID 19900287, 2009). "Tumor-associated Tregs express the IL-23 receptor, which activates STAT-3 in this cell type, leading to upregulation of the Treg-specific transcription factor FoxP3 and the immunosuppressive cytokine IL-10." (PMID 19900287, 2009). "STAT3 is known to be a substrate for SFK members, and SFK inhibition in various carcinoma tumor cell lines results in loss of STAT3 activity." (PMID 20182632, 2009). "In tumor cells, STAT3 activation has been linked to both inhibition of pro-inflammatory cytokine secretion and induction of anti-inflammatory cytokine secretion, such as IL-10 and VEGF." (PMID 19718269, 2009). "Tumor immune escape and angiogenesis contribute to tumor progression, and gangliosides and activation of signal transducer and activator of transcription (STAT)-3 are implicated in these processes." (PMID 19519895, 2009). "Dysregulation of signal transducer and activator of transcription 3 (STAT3) has been implicated as a key participant in tumor cell survival, proliferation, and metastasis and is often correlated with a more malignant tumor phenotype." (PMID 19284568, 2009). "STAT1 plays a prominent role in the effector immune response, whereas STAT3 is implicated in tumor progression and down-regulation of the response to type I IFNs." (PMID 18954464, 2008).
tumor (continued). "A growing number of human malignancies and tumour formation are associated with high levels of activation of signal transducers and activators of transcription (STATs), very frequently Stat3 and Stat5." (PMID 17311011, 2007). "STAT3 activation is implicated in tumour invasion in head and neck squamous cell and other carcinomas." (PMID 16804520, 2006). "Developmental pathways, including hedgehog, Notch, IL6/JAK/STAT3, and TGFβ signaling, along with hallmarks linked to tumor progression, stemness capacity, and metastasis (e.g., angiogenesis and EMT), displayed a significant positive association with WNTHigh populations." (PMID 41117706, 2026). "Additionally, STAT3 is known to play a key role in tumor immunity, while other STAT family members are linked to the promotion of cancer development." (PMID 40830747, 2025). "These oncogenic features of SOX17 and SOX18 are supported by their significant co-expression with endothelial and inflammatory mediators such as VCAM1 and STAT3, both of which are known to drive tumor-associated angiogenesis, immune evasion, and metastatic potential." (PMID 41373817, 2025). "Therefore, SLC9A2’s inhibition of tumor angiogenesis is associated with its suppression of the STAT3 signaling pathway." (PMID 40474298, 2025). "Clinically, aberrant STAT3 signaling is implicated in multiple diseases, with constitutive activation often correlating with poor prognosis in cancer due to its involvement in sustaining tumor growth and survival." (PMID 40704145, 2025). "However, when this pathway is aberrantly activated, STAT3 regulates the transcription and abnormal expression of downstream molecules associated with tumor progression." (PMID 40936898, 2025). "JAK/STAT3 hyperactivation in tumor cells may occur as a result of elevated IL-6 levels in the serum and/or in the tumor microenvironment or loss-of-function mutations affecting negative regulators of STAT3." (PMID 40428422, 2025). "However, STAT3 is generally considered to be the more prominent oncogenic target due to its association with a wide range of tumor types." (PMID 40075607, 2025). "Notably, STAT3 has been shown to be overexpressed in tumor tissues of patients with OS, and high STAT3 protein levels were associated with increased metastasis and reduced disease-free and overall survival." (PMID 40099972, 2025). "Cytomegalovirus might serve as a causative agent in GBM through ARG2 upregulation and STAT3 signaling, which is often used as an early tumor biomarker." (PMID 40558592, 2025). "Furthermore, the STAT3 signaling is also linked to the tumor immune response, and plays significant roles in suppressing key immune activation regulators while facilitating the release of immunosuppressive factors." (PMID 40369667, 2025). "Furthermore, deficiency of circRNA-14,052 reduced xenograft tumor growth in vivo through targeting miR-214-3p/IKBKB/IL-6/JAK2/STAT3 axis." (PMID 41044672, 2025). "To gain deeper insight into the phenotypical alteration of STAT3-deficient neutrophils, we performed high-parameter single-cell flow cytometry analysis and observed significant changes in the myeloid cell landscape of the tumor." (PMID 40885734, 2025). "Additionally, IL-22, which is functionally associated with IL-23R signaling, has been implicated in promoting Sorafenib resistance in HCC through STAT3 activation, leading to enhanced tumor cell survival and decreased apoptosis." (PMID 39921803, 2025). "Additionally, tumor-associated macrophages (TAMs) contribute to OS metastasis by activating the COX-2/STAT3 axis, which promotes EMT and enhances invasion potential in cell and mouse models." (PMID 40941019, 2025). "Moreover, PD-1+ M2-like tumor-associated macrophages have been shown to exhibit STAT3-mediated immunosuppressive programming, which can be reversed by PD-L1 blockade." (PMID 40558486, 2025).